NAGA (alpha-N-acetylgalactosaminidase)
Description:
Removes terminal alpha-N-acetylgalactosamine residues from glycolipids and glycopeptides. Required for the breakdown of glycolipids.
Synonyms: D22S674; GALB
Tractability: Small molecule: a structure with a bound ligand is known. Antibody: UniProt predicts a signal peptide or a membrane-spanning region. PROTAC: ubiquitination databases record sites on it; its protein half-life has been measured.
Target class: Enzyme; Hydrolase
Gene: Protein-coding gene on chromosome 22 (42,058,334 to 42,071,198, reverse strand). Ensembl gene ENSG00000198951.
Subcellular location: Lysosome
Gene Ontology:
Molecular function: alpha-N-acetylgalactosaminidase activity; protein homodimerization activity; alpha-galactosidase activity; hydrolase activity, hydrolyzing O-glycosyl compounds
Biological process: carbohydrate catabolic process; glycolipid catabolic process; glycoside catabolic process; oligosaccharide metabolic process; carbohydrate metabolic process
Cellular component: extracellular exosome; lysosome; cytoplasm
Genetic constraint (gnomAD): Loss-of-function variants: 45 observed, 51.49 expected, observed/expected ratio (o/e) 0.87, 90% interval 0.69 to 1.12. The upper end of that interval is the gene's LOEUF score, 1.12, which puts it in group 4 of 6, group 1 being the genes least tolerant of losing a copy. Missense variants: 493 observed, 562.24 expected, observed/expected ratio (o/e) 0.88, 90% interval 0.81 to 0.94. Synonymous variants: 176 observed, 210.05 expected, observed/expected ratio (o/e) 0.84, 90% interval 0.74 to 0.95.
Gene-disease validity (ClinGen):
ClinGen rates the evidence that NAGA causes each of these diseases.
alpha-N-acetylgalactosaminidase deficiency (autosomal recessive): Definitive. Alpha-N-acetylgalactosaminidase (NAGA) deficiency is a very rare lysosomal storage disease that is clinically and pathologically heterogeneous and is characterized by deficient NAGA activity.
Homologues: Orthologues: chimpanzee NAGA (99% identical), macaque NAGA (98% identical), guinea pig NAGA (84% identical), mouse Naga (82% identical), rat Naga (82% identical), pig NAGA (79% identical), rabbit NAGA (78% identical), dog NAGA (78% identical), zebrafish naga (66% identical), tropical clawed frog naga (55% identical), Drosophila melanogaster CG5731 (50% identical), Drosophila melanogaster CG7997 (46% identical), and 1 more. Paralogues in human: GLA (48% identical).
Diseases named in the same sentence as NAGA in open-access papers:
NAGA is named in the same sentence as 31 diseases in open-access papers, as found by Europe PMC text mining. Sharing a sentence is not in itself a finding about the gene and the disease. The quoted sentences say what the papers report.
Kanzaki disease (5 papers, 2011 to 2025). "Mutations in GUSB, CLN6, and PPT1 cause Sly disease, neuronal ceroid lipofuscinosis (CLN6), and neuronal ceroid lipofuscinosis (CLN1), respectively, whereas mutations in GALNS and NAGA cause Morquio A disease and Schindler disease/Kanzaki disease, respectively." (PMID 34867278, 2021). "Mutations in NAGA have been identified as the cause of Kanzaki disease, which may involve neurologic complications in the CNS and peripheral nervous system." (PMID 21629698, 2011). "Alpha-N-acetylgalactosaminidase is an isoenzyme of alpha-galactosidases that functions in the lysosome and is related to Schindler disease and Kanzaki disease with variable neuroaxonal dystrophy and neurological signs." (PMID 35571611, 2022).
Schindler disease (5 papers, 2013 to 2022). "Schindler’s disease, caused by a mutation in the NAGA gene causing alpha-N-acetylgalactosaminidase enzyme deficiency, affects breaking down of glycoproteins and glycolipids." (PMID 33179602, 2020). "The third shared heterozygous variant of the parents NM_000262: c.973G > A, p.(Glu325Lys) in the NAGA gene is described to lead to Schindler disease Type 1 when found homozygous in children." (PMID 29373990, 2018). "Mutations in NAGA have been associated with Schindler disease, whereas mutations in PRPF39 have not been correlated with any specific disease." (PMID 23890092, 2013).
schizophrenia (5 papers, 2022 to 2025). A major psychotic disorder characterized by abnormalities in the perception or expression of reality. "NAGA was proposed as a genetic risk for schizophrenia because it encodes the lysosomal enzyme alpha-N-acetylgalactosaminidase, which is necessary for the breakdown of glycolipids and helps to maintain and regulate the dendritic spine." (PMID 37628788, 2023). "ENST00000407991 of CHRNA2 was significantly associated with schizophrenia only in Brain-Cerebellum, while ENST00000396398 of NAGA was significantly associated with schizophrenia in all the five optimized brain regions." (PMID 35412455, 2022). "For example, NAGA and CHRNA2 were reported to be associated with schizophrenia by three and seven research papers in the PubMed database, respectively." (PMID 35412455, 2022). "Specifically, AGER, PDIA3 and NAGA appeared to have an effect on schizophrenia." (PMID 40281223, 2025).
lysosomal storage disorder (2 papers, 2024 to 2025). "NAGA encodes the alpha-N-acetylgalactosaminidase, a lysosomal enzyme whose deficiency causes a rare autosomal recessive lysosomal storage disorder." (PMID 40400026, 2025).
ovarian carcinoma (2 papers, 2014 to 2022). A malignant neoplasm originating from the surface ovarian epithelium. "However, the epigenetic modification of the NAGA gene by DNA hypermethylation reduced the expression of α-NaGalase and increased chemoresistance to cisplatin in ovarian cancer." (PMID 36662206, 2022). "One branch clustered eight genes (NAGA, B4GALT6, HEXA, GLB1, GBA, GLA, UGCG, HEXB) with generally comparable expression levels among the cell lines, except for the UGCG gene which was expressed at considerably higher levels in both HOSE cell lines compared with the ovarian cancer cell lines." (PMID 25294702, 2014).
glioma (1 paper, 2020). A benign or malignant brain and spinal cord tumor that arises from glial cells (astrocytes, oligodendrocytes, ependymal cells). "Through high-throughput expression profiling, WGCNA, lasso, and multivariate Cox analysis, we acquired eight genes (HCK, HAVCR2, CD37, LPAR5, NAGA, C1QC, FCER1G and AIF1) to construct the MRGs signature in Grade II/III glioma patients." (PMID 33186124, 2020).
scrapie (1 paper, 2011). A fatal disease of the nervous system in sheep and goats, characterized by pruritus, debility, and locomotor incoordination. "In the present study, we observed a slight but significant increase of NAGA expression in scrapie medullae and a positive association between the expression of this gene and both prion deposition and astrogliosis." (PMID 21629698, 2011).
type 1 diabetes (1 paper, 2020). "Singh and colleagues also reported that youths with type 1 diabetes excreted higher amounts of lumican, CD14, and various lysosomal proteins such as ASAH1, CTSD, and NAGA compared to their non-diabetic siblings." (PMID 32453760, 2020).
infection (3 papers, 2018 to 2025). The state of being infected such as from the introduction of a foreign agent such as serum, vaccine, antigenic substance or organism. "Overall, our data indicate that NagA is a key player in recycling remodeled PG fragments in mycobacteria, contributing to the control and use of scarce nutrient resources during infection." (PMID 40818611, 2025). "But very little is known about the role of NagA in mycobacterial cells; however, proteomic profiling identified NagA is present in lung tissues from guinea pigs infected with Mtb, pointing toward a potential role in Mtb during infection." (PMID 40818611, 2025).
tumor (3 papers, 1998 to 2025). "Glycolipid catabolism involving proteins such as GM2A, NAGA, and SGSH is more active in patients with a low necrosis rate, which may be closely related to the energy metabolism needs of tumor cells." (PMID 40989695, 2025).
NAGA also shares sentences with these, for which no sentence is quoted: cancer (5 papers); Schindler disease type I (3); Cognitive impairment (2); duodenal adenocarcinoma (2); melanoma (2); Alzheimer disease (1); Angiokeratoma corporis diffusum (1); bipolar disorder (1); Blindness (1); colon carcinoma (1); colorectal adenocarcinoma (1); Fabry disease (1); gastric adenocarcinoma (1); major depression (1); mental disorder (1); Morquio A disease (1); neuroaxonal dystrophy (1); neuronal ceroid lipofuscinosis (1); optic atrophy (1); prion disease (1); psychiatric disorder (1).